PAX8 (paired box 8)
Diseases named in the same sentence as PAX8 in open-access papers (continued):
Sharing a sentence is not in itself a finding about the gene and the disease.
thyroid cancer (continued). "The expansion of knowledge regarding genetic mutations in thyroid cancers has led to the use of molecular markers as an indicator of prognosis and for the malignancy diagnosis especially in indeterminate FNA samples (BRAF, RAS, RET/PTC, and PAX8/PPARγ)." (PMID 23326756, 2012). "Microarray analyses of 24 thyroid carcinomas – 7 classic papillary, 8 follicular variants of papillary (fvPTC), 4 follicular (FTC) and 5 PDTC – were performed and correlated with RAS, BRAF, RET/PTC and PAX8-PPARG alterations." (PMID 19809427, 2009). "In addition, we found that METTL3 expression not only increased the levels of PAX8 but also inhibited the expression of NIS in tissue samples, which indicates that METTL3 relies on the expression of PAX8 to increase the sensitivity to chemotherapy drugs for thyroid cancer." (PMID 38993572, 2024). "Finally, we further determined whether METTL3 mediates malignant behavior of thyroid cancer cells dependent on PAX8 in vivo." (PMID 38993572, 2024). "Notably, ectopic overexpression of PAX8 in FB-2 thyroid cancer cells promotes Neuropilin-2 downregulation producing a significant reduction in cell proliferation, migration ability, and invasion activity and reverting the cell phenotype from mesenchymal to a more epithelial one." (PMID 26030152, 2015). "AsuragenmiR Inform (Austin, TX, USA) mutation analysis assay and Thyroid Cancer Mutation Panel by Quest Diagnostics (Madison, NJ, USA) are the two main commercially available mutational tests which test for known genetic alterations such as BRAF, RAS, RET/PTC, and PAX8/PPARγ." (PMID 24808946, 2014). "Chromosomal rearrangements involving genes known to be translocated in thyroid cancer were found in two samples, including one case with RET rearrangement involving the common RET partner CCDC6 and one case with the PAX8::PPARG fusion." (PMID 41123735, 2025). "For example, low expression of PAX8 inhibits the expression of NIS, leading to the dedifferentiation of thyroid cancer cells." (PMID 40819127, 2025). "Detection of PAX8 and Tg is recommended when it is difficult to distinguish MLA from thyroid carcinoma." (PMID 39980562, 2025). "Thyroid differentiation-related genes (TG, TSHR, and PAX8) were upregulated in PTC-Epis and downregulated in ATC-Epis, which revealed a potential dedifferentiation process in thyroid cancer progression." (PMID 38478516, 2024). "Of interest, the effect of PAX8 expression of cancer cell proliferation and migration is relatively minor, and TTF1 has a more pronounced effect on the tumorigenic properties of thyroid cancer cells." (PMID 35806410, 2022). "We studied the expression of NKX2-1, PAX8, and DICER1 in the three thyroid cancer cell lines concurrently." (PMID 33176626, 2021). "This allowed NIS, PAX-8, TTF-1, TTF-2, and TSHR gene expression to promote redifferentiation of thyroid cancers." (PMID 33995657, 2021). "Molecular testing has been increasingly utilized to assist with indeterminates as approximately seventy percent of differentiated thyroid cancers have detectable abnormalities involving BRAF, RAS, RET/PTC, or PAX8/PPAR gamma." (PMID 33763983, 2021). "DICER1, NKX2-1, PAX8, and CREB expression levels were evaluated by gene and protein expression in vitro and by interrogation of The Cancer Genome Atlas (TCGA) thyroid cancer data." (PMID 33176626, 2021). "For example, PAX8 and GUF1 were reported as prognostic markers for endometrial cancer, renal cancer and thyroid cancer, respectively." (PMID 34108011, 2021).
thyroid cancer (continued). "In thyroid carcinoma, Pax8 exists as a gene fusion with peroxisome proliferator activated receptor gamma (Pax8/PPARG gene fusion), resulting in an oncogenic Pax8–PPARγ fusion protein." (PMID 34195082, 2021). "Metastatic tumors that contain clear cells are most likely renal cell carcinoma, clear cell breast carcinoma or thyroid carcinoma and, therefore, immunomarkers such as RCC, CD10, PAX8, ER/PR, TTF-1 are useful." (PMID 32642935, 2021). "In the molecular diagnosis of thyroid cancer, the related molecular markers include TERT, BRAF, PAX8/ PPARγ, RAS and RET/PTC26." (PMID 31949496, 2020). "The follicular cells of the thyroid gland require the PAX8 gene, and the rearrangement of PAX8 might be related to thyroid tumors, which is in accordance with the representation of the pathway that PAX8 was mainly involved in thyroid hormone synthesis and thyroid cancer pathways." (PMID 29326596, 2017). "In contrast, the motility of the two overexpressing PAX8 clones is significantly decreased; suggesting that NRP2 downregulation strongly reduces the migration ability of FB-2 thyroid cancer cells." (PMID 26030152, 2015). "The expression of Pax-8 and TTF-1 is low in thyroid carcinoma; and stable transfection with a Pax-8 expression vector in anaplastic thyroid carcinoma cell line, ARO, caused re-expression of endogenous NIS, TG, and TPO." (PMID 18682709, 2008). "In thyroid malignancies, excluding well-differentiated thyroid cancers, the paired box gene 8 (PAX-8) protein is considered a more sensitive indicator of thyroid origin than TTF-1 or thyroglobulin; however, PAX-8 is present in limited quantities in primary squamous cell carcinomas." (PMID 40061900, 2025). "Expression of GATA-3 supports a breast origin, while the absence of PAX-8 helps exclude primary thyroid carcinoma." (PMID 41556026, 2025). "The thyroid specific biomarkers of TTF-1 and PAX8 are usually positively expressed in primary thyroid cancer and were absent in our case." (PMID 37032350, 2023). "FOXE1 is another suggested PAX8 target gene in thyroid development that to the best of our knowledge was not shown to be a PAX8 target gene in thyroid cancers." (PMID 35806410, 2022). "The role of PAX8 itself in thyroid carcinomas that do not harbor the PPFP fusion protein is unclear." (PMID 35806410, 2022). "As these thyroid cancer cells expressed PAX8 but not NKX2-1, cell death was seemingly due to the effects induced by NKX2-1 re-expression." (PMID 34748583, 2021). "The thyroid-specific genes TSHR, PAX-8, and NIS were significantly upregulated, and improved RAI uptake was noted, whereas expression of CD97, an undifferentiation marker, declined in dedifferentiated thyroid cancers." (PMID 33995657, 2021). "As noted, primary differentiated thyroid cancer commonly is TG, TTF-1 and PAX8 positive." (PMID 33776925, 2021). "Sanger sequencing of primary and metastatic tissues ruled out the presence of any mutations in known thyroid-cancer–related genes (H-, K-, N-RAS, BRAF, PTEN, PIK3CA), and PAX8-PPARG fusions were excluded by RT-PCR." (PMID 32674319, 2020). "The thyroid cancer TPC1 cell line expressed Gp78/AMFR and PAX-8 mRNA." (PMID 31431834, 2019). "Previously reported fusion genes in thyroid cancer, ETV6–NTRK3 (4.80% in PTC), CCDC6–RET (2.40% in PTC), NCOA4–RET (0.80% in PTC), SQSTM1–NTRK1 (0.80% in PTC), STRN–ALK (0.80% in PTC), and PAX8–PPARG (0.80% and 1.82% in PTC and FTN, respectively), were also identified." (PMID 27494611, 2016). "To examine whether high levels of NRP2 could directly contribute to the tumorigenicity of thyroid cancer cells, we analyzed whether NRP2 downregulation, mediated by PAX8 re-expression, was able to modify the oncogenic properties of FB-2 cells." (PMID 26030152, 2015).
thyroid cancer (continued). "However, human ChIP-seq data would be difficult if not impossible to obtain due to the fact that antibodies to endogenous PPFP also bind to PAX8 or PPARG (our PPFP is epitope-tagged), as well as the fact that PPFP thyroid carcinomas are uncommon." (PMID 26595524, 2015). "Furthermore, we demonstrated an inverse correlation between expression of PAX8 and STK17B in a set of cell lines derived from human thyroid carcinomas." (PMID 24086368, 2013). "KTC-1 cells show relatively higher PAX-8 and TTF-1 transcripts among thyroid cancer cell lines." (PMID 21556376, 2011). "The authors suggested that miR-146b-3p/PAX8 (Paired box gene 8)/NIS regulatory axis might be a relevant therapeutic target to modulate thyroid cell differentiation and iodide uptake for improved treatment of advanced thyroid cancer." (PMID 34072348, 2021). "The expression of PAX8 and HNF1B across normal tissues also supported their tissue specificity, and the extremely high expression of PAX8 in the thyroid could indicate its potential dependency role in thyroid cancer." (PMID 33850477, 2021). "Furthermore, we would suggest incorporating PAX8 in the panel, which, although non-specific for the renal origin (being positive in endometrial, ovarian and thyroid cancers), has been proven useful in primary and metastatic RCCs." (PMID 32316524, 2020). "PAX8 may be diagnostically useful to distinguish these Napsin A-positive and Thyoglobulin-negative thyroid carcinomas from lung adenocarcinomas, which are PAX8 negative." (PMID 29621151, 2018). "Interestingly, we observed an inverse correlation between the expression of PAX8 and Neuropilin-2 in thyroid carcinoma tissues and cell lines compared to non-tumor counterparts, suggesting a critical role of PAX8 in regulating Neuropilin-2 expression in vivo." (PMID 26030152, 2015). "We subsequently observed a consistent result in a series of thyroid cancer cell lines from different human tumors; high STK17B expression was observed in the most undifferentiated human anaplastic thyroid cells (8505c, Hth7 and Hth83), which are characterized by very low or null PAX8 levels." (PMID 24086368, 2013). "However, the rationale for administration of PPARγ ligands to treat thyroid cancer is not clear as some studies have shown a reduction in PPARγ expression, yet others revealed normal PPARγ expression or the occurrence of PAX8-PPARγ which can inactivate rather than decreasing PPARγ in thyroid cancer." (PMID 34557159, 2021). "Primary thyroid carcinomas typically express TG, TTF-1, and PAX8, whereas these markers are generally absent in metastatic lesions." (PMID 41018104, 2025). "IHC staining of the tumor in the neck showed diffuse expression of PAX8 and TTF1, indicating thyroid origin, and negative staining for thyroglobulin, calcitonin, PTH, and GATA3, which support a diagnosis of an oncocytic poorly differentiated thyroid carcinoma." (PMID 40277780, 2025). "In addition, cell death was not induced in MDCK kidney cells expressing PAX8, but not NKX2-1, whose expression pattern is identical to that of the thyroid cancer cells used in this study." (PMID 34748583, 2021).
ovarian carcinoma (103 papers, 2006 to 2026). A malignant neoplasm originating from the surface ovarian epithelium. "Among the CDK12/13-targets involved in transcription, PAX8 is a well-established diagnostic marker of ovarian cancer." (PMID 37202753, 2023). "More importantly, RNAscope with a sequence specific probe confirmed that the bona fide epithelial ovarian cancer cells, stained with PAX8 MAb, expressed αSMA RNA encoded by the ACTA2 gene." (PMID 35055018, 2022). "Our data suggest that deregulation of PAX8 expression, which is the hallmark of ovarian cancer, is critical for ovarian cancer initiation and progression." (PMID 34965417, 2021). "After confirmation of ADSCs causing PAX8 overexpression in ovarian cancer cells, the role of PAX8 in regulating cancer cell proliferation was investigated next." (PMID 33830648, 2021). "PRDM3 is amplified in ovarian cancers and we show that the MECOM locus and PAX8 sustain in vivo tumor growth, further supporting that the identified function of the MECOM locus underlies PAX8-driven oncogenic functions in ovarian cancer." (PMID 33903593, 2021). "As we have analyzed above, PAX8, encoding a functional transcription factor, has a uniquely high expression pattern in ovarian-cancer-derived PDX tumor tissues, corresponding with Rule-5." (PMID 31456818, 2019). "Recently, gene expression profiling studies have indicated that the transcription factor PAX8 is a potential diagnostic marker for ovarian carcinoma." (PMID 24766781, 2014). "In conclusion, understanding PAX2’s and PAX8’s distinct roles in ovarian tumorigenesis helps refine diagnostic and prognostic strategies and offers potential avenues for developing targeted therapies to treat ovarian cancer more effectively." (PMID 40506992, 2025). "SLC34A2 is also regulated by PAX8, a master transcription factor associated with ovarian cancer cell survival and the development of female reproductive systems, suggesting that SLC34A2 may play an important role in tumorigenesis." (PMID 40836974, 2024). "Although the specific mechanisms of how ADSCs mediate the TAZ stability in ovarian cancer cells through PAX8 were still unclear, an association between ADSCs, PAX8 and TAZ in ovarian cancer sheds novel light on the mechanism of ADSCs advancing the ovarian cancer metastasis." (PMID 33830648, 2021). "In summary, our analyses reveal that PAX8 is closely associated with ovarian cancer and may involve in the changes of ovarian cancer cells mediated by ADSCs." (PMID 33830648, 2021). "Therefore, the PAX8 gene is being considered as a potential effective diagnostic marker of ovarian cancer." (PMID 34540435, 2021). "PAX8 silenced cells show a lower percentage of cell-survival compared to that of the parental cells indicating that the loss of PAX8 brings to an increased sensitivity to anoikis of ovarian cancer cells and accordingly decreased bcl-2 and increased Bax expression." (PMID 31832016, 2019). "Moreover, we suggest a possible role for PAX8 in the peritoneal dissemination of ovarian cancer cells by modulating cancer cells’ anoikis-susceptibility and the interaction of tumor cells with the extracellular matrix (ECM)." (PMID 31832016, 2019). "PAX8 may also be be involved in genetic susceptibility to ovarian cancer, possibly with subtype-specific biological roles in EOC initiation." (PMID 29312534, 2017). "In conclusion, we think that the majority of the genes affected by PAX8 silencing are associated with important biological cellular processes and we believe that our analysis provides a solid basis for the identification of relevant molecules involved in ovarian cancer." (PMID 27259239, 2016). "Markers such as Cytokeratin 7, PAX8, and E-cadherin provide critical insights into various aspects of ovarian cancer research." (PMID 40034272, 2025). "Among these, PAX8 expression was high in ovarian cancer cell lines, whereas cytokeratin 7 expression was high in IHOSE cell lines." (PMID 40034272, 2025).
ovarian carcinoma (continued). "In ovarian cancer, the transcription factor PAX8 has been found to interact with SOX17 to promote angiogenesis, a crucial process for tumor growth and metastasis." (PMID 38981872, 2024). "In the clinical setting, Ki67 serves as a prognostic marker for ovarian cancer, reflecting cellular proliferation rates, while PAX8 identifies the gynecological origin of the malignancy, correlating with patient outcomes." (PMID 39206413, 2024). "Contrastingly, PAX8 occupies de novo binding sites in ovarian cancer cells relative to healthy tissue." (PMID 39536500, 2024). "Another example is the dependence of PAX8, a prototype lineage-survival oncogene in epithelial ovarian cancer, on HDAC inhibition through the perturbation of the super-enhancer topology associated with the PAX8 gene locus." (PMID 37190100, 2023). "Lung adenocarcinoma-related markers were evaluated including Thyroid transcription factor-1 (TTF-1) and Napsin A, and ovarian cancer-related markers including pair box gene 8 (Pax-8) and Wilm’s tumor gene 1(WT-1)." (PMID 37337182, 2023). "The two markers, WT-1 and PAX8, are commonly used to differentiate ovarian cancer from other tumors of epithelial origin." (PMID 37337182, 2023). "Representative images of LGSOC tumors revealed the presence of alfa-smooth muscle actin positive CAF surrounded by tubular structures that stained positive for the ovarian cancer cell marker PAX8." (PMID 37853495, 2023). "The results showed that the PAX8 gene expression level of ovarian cancer cells was decreased after transfection with low knockdown plasmid compared with the control group, and the difference was statistically significant." (PMID 35548853, 2022). "We show here that, minimizing manipulation, we have been able to determine that spheroids from EOC are all almost exclusively made of PAX8+, i.e., epithelial ovarian cancer cells." (PMID 35055018, 2022). "PCR results showed that PAX8 expression in ovarian cancer tissues was significantly higher than that in adjacent control tissues." (PMID 35548853, 2022). "This study showed that the expression of PAX8 in ovarian cancer tissues was significantly higher than that in adjacent tissues." (PMID 35548853, 2022). "It has been reported that PAX8 controls the cell cycle and metabolic gene expression program in ovarian cancer cells by binding to enhancers." (PMID 35548853, 2022). "The presence of ovarian cancer cells in fresh-frozen tumour sections was confirmed using PAX8 immuno-fluorescence prior to nuclear F-actin staining." (PMID 35693931, 2022). "PCR results showed that PAX8 was expressed in both ovarian cancer and para-cancer tissues, and the expression in ovarian cancer tissues was significantly higher than that in para-cancer control tissues." (PMID 35548853, 2022). "PAX8 is a regulator of embryonic tissue development and cell differentiation, and is highly expressed in epithelial ovarian cancer tissues." (PMID 35548853, 2022). "Curcumol can inhibit the invasion, migration and epithelial-mesenchymal transformation of IGROV-1 and OVCAR-3 cells in ovarian cancer, and its mechanism is related to the targeted inhibition of PAX8." (PMID 35548853, 2022). "Immunofluorescence revealed that aggregates are made almost exclusively of ovarian cancer cells expressing the specific nuclear PAX8 protein." (PMID 35055018, 2022). "Both genome-wide shRNA knock-down (KD) and CRISPR knock-out (KO) screens have demonstrated this lineage dependency in which PAX8 KD and KO result in ovarian cancer lineage growth arrest." (PMID 34290299, 2021). "Based on these data, it can be confirmed that ADSCs induce an overexpression of PAX8 in ovarian cancer cells." (PMID 33830648, 2021).